CD28 (CD28 molecule)
Diseases named in the same sentence as CD28 in open-access papers (continued):
Sharing a sentence is not in itself a finding about the gene and the disease.
influenza (continued). "Therefore, rather than stimulation with HLA-matched peptides, we chose to expose the PBMCs to either an influenza viral peptide pool containing 12 influenza viral peptides spanning 10 HLA subtypes or beads coated with anti-CD3/anti-CD28." (PMID 38214784, 2024). "Most influenza reactive T cells from the young donors express both CD28 and CD27 on their surface." (PMID 21887299, 2011). "Moreover, CD28+ expression is said to be directly related to influenza vaccine response." (PMID 36298529, 2022). "In humans, the loss of CD28 expression on CD8+ T cells in association with the late stage or terminal differentiation of these memory T cells would predict a defective effector phase and early apoptosis of the effector CD8+ T cells responding to influenza challenge." (PMID 27322555, 2016). "In addition, the early change/increase of CD4+ T cell CD28 expression at Day 3 (relative to baseline) was significantly correlated with the observed increase in the influenza-specific B cell ELISPOT response at Day 28 post-vaccination compared to baseline (r = 0.216, p-value = 0.031)." (PMID 25816015, 2015). "Based on reported alterations in T cell memory phenotype associated with aging and impaired antibody responses to the influenza vaccine, CD8+ naive cells (CD45RA+ CCR7+) and CD8 + CD28- TEMRA cells (CD45RA+ CCR7- CD28-) were selected for assessment." (PMID 36650551, 2023). "There is little data on this currently; however, in the context of influenza infection, it has been shown that at least some tissue-resident memory CD8 T cells in the lung are reliant on CD28 costimulation." (PMID 36017489, 2021). "Further, the influenza specific memory CD8 T-cell response retained stable expression of the exhaustion marker programmed death-marker-1 (PD-1) and co-stimulatory molecule CD28 following infection with SIV." (PMID 22403659, 2012). "Vaccine-induced SIV-specific CD8 T-cells express similar levels of CD28 to influenza-specific CD8 T-cells prior to SIV infection, but following infection CD28 expression on the effector SIV-specific CD8 T-cells decreases substantially." (PMID 22403659, 2012). "Therefore, significantly decreased expression of CD28, CD40L, IL12R, and CD69 in obese subjects leads to markedly lower activation of CD4+ and CD8+ T cells after influenza vaccination." (PMID 36295052, 2022). "With regard to splenic ILC1s, influenza infection alone resulted in an up-regulated expression of CD28 that was not further boosted by the pre-activation of iNKT cells." (PMID 31440243, 2019). "IL-2 treatment has been shown in the mouse to restore the effector phase of the response to influenza in the absence of CD28 costimulation." (PMID 27322555, 2016). "Our univariable analysis found consistent (although weak) correlations between the expression levels of CD28 on both CD8+ and CD4+ T cells and influenza vaccine-induced memory-like IgG B cell ELISPOT response measured at different timepoints, but not antibody titers." (PMID 25816015, 2015). "We assessed the correlations between influenza vaccine-specific humoral immunity measures and other overall humoral immune response variables measured over time, and age/immunosenescent markers (TREC, TERT, CD28 expression on CD4+ and CD8+ T cells)." (PMID 25816015, 2015). "The observation that fewer Tfh cells form after influenza infection in Cd28flox/floxOx40cre/+ mice suggests that their formation and/or maintenance is impaired in the absence of CD28." (PMID 25347065, 2014). "People with high numbers of lymphocytes negative for CD28 show reduced responses to influenza vaccines as well as an increase in inflammatory diseases and inflammatory responses to immune stimuli." (PMID 25244034, 2014). "The proportion of CD28-negative Th1 cells in the lung remained constant between 5 and 14 days post influenza infection, suggesting that, unlike Tfh, continued CD28 expression is dispensable for Th1 maintenance." (PMID 25347065, 2014).
influenza (continued). "CD8 activation peaked 6–8 days after mild influenza onset, when 13% (6–22%) were HLADR+CD38+, and was accompanied by a significant loss of resting/CD27+CD28+ cells without accumulation of CD27+CD28− or CD27−CD28− cells." (PMID 22363665, 2012). "We found a higher proportion of the influenza responsive CD8 and CD4 T cells were of this late effector CD45RA+ phenotype, and that CD8 but not CD4 T cells had also significantly lost expression of costimulatory molecules CD28 and CD27." (PMID 21887299, 2011). "Thus, we next examined AT2 in vivo flu peptide/MHCII complex formation, by co-culturing in vivo-infected AT2s from wild-type or MHCII−/− B6 mice taken 4 days post influenza infection with polyclonal splenic CD4+ or CD8+ T cells taken 9 days post-infection, in the presence of soluble anti-CD28." (PMID 34183650, 2021). "To determine whether this antibody could enhance CD8+ T cell function, we cultured PBMCs from healthy donors with anti-CD28 antibody in the presence of influenza (Flu) peptide (GILGFVFTL) with or without anti-hCEACAM1 mAb." (PMID 29967450, 2018). "In our study, in the influenza-specific CD8+ T cells there was not a predominant population based on CD27 and CD28 expression." (PMID 22920436, 2012).
diabetes (35 papers, 2009 to 2025). "Previous reports showed that injection of the dsRNA mimic poly(I∶C) (200 μg) into Treg-deficient CD28−/− NOD mice at 8 weeks of age led to rapid development of diabetes within 1–6 days after administration that showed a fulminant T1D-like phenotype." (PMID 25343451, 2014). "In chronic-inflammation situations such as chronic kidney disease and diabetes mellitus (DM), the transformation of receptor repertoire on T cells, including the loss of the CD28 molecule, results in a cell type of which the phenotype and activities resemble NK cells, called the NK-like T cell." (PMID 33804135, 2021). "Deletion of Treg cells could accelerate T1D onset because spontaneous diabetes was exacerbated in both B7-1/B7-2-deficient and CD28-deficient NOD mice." (PMID 28420440, 2017). "Thus, exacerbation of diabetes by CD28 deficiency in NOD mice and the reciprocal protection by CD28 costimulation in neonatal NOD and T cell depletion with anti-CD3 antibodies point to Treg as the primary mechanism responsible for immunomodulation." (PMID 21738739, 2011). "Obarorakpor and colleagues also targeted IAg7/insulin B9-23, and protected NOD.CD28-/- mice which develop accelerated diabetes." (PMID 39351219, 2024). "In case–control studies, patients with diabetes had higher blood levels of CD4+CD28− and CD4+ & CD8+ T effector memory RA+ (TEMRA) cells compared to those without diabetes." (PMID 36333945, 2023). "This makes the NOD.CD28-/- mouse model reliable and sensitive in detecting changes in diabetes development and progression." (PMID 37593744, 2023). "Our group has previously shown that CD4+ CD28- T cells are also increased prior to the development of incident diabetes in PWH." (PMID 36865544, 2023). "First, spontaneous diabetes incidence is increased to 100% and disease onset is accelerated in NOD mice deficient in either CD28 or CD80 and CD86 that is directly correlated with a quantitative decrease in Tregs by >80%." (PMID 31281853, 2019). "Taken together, B7/CD28 co-stimulation has divergent effects on the pathogenesis of diabetes mellitus in the different context of disease, which leads to a great barrier for the therapeutic method in diabetes." (PMID 29416823, 2018). "Taken together, above studies of B7/CD28 co-stimulatory molecules show a complicated role in development of immune-mediated disease, including diabetes." (PMID 29416823, 2018). "While not only complicated role of B7/CD28 dyad, many other co-stimulatory molecule dyads also exhibit a dichotomous role in the pathogenesis of diabetes." (PMID 29416823, 2018). "Here, we review dichotomous role of these co-stimulatory molecules serve complicated roles in diabetes mellitus, especial B7/CD28." (PMID 29416823, 2018). "CD28 and CD40 have disparate effects on inducing these T cell fates in NOD mice, as a loss of CD28 can restore diabetes in CD40L-deficient mice and alters the number of Tregs in those mice." (PMID 26124756, 2015). "mRNA expression of the activated lymphocytes showed that diabetes impaired the Akt1 (234 ± 9.5), CD28 (229 ± 14) and Cdc42 (33 ± 6.5) signaling compared to those of the control group [Akt1 (252 ± 12), CD28 (235 ± 10), Cdc42 (45 ± 5.0)]." (PMID 25009576, 2014). "Antigen-activated lymphocytes showed that diabetes impaired the mRNA expression of the protein kinase B (Akt1), Cdc42, and the co-stimulatory molecule, CD28, which are important for cell survival, actin polymerization and T cell activation, respectively." (PMID 25009576, 2014). "This conclusion was supported by results showing that anti-GITR antibody exacerbates diabetes also in CD28−/− NOD mice, which lack Tregs." (PMID 19936238, 2009). "Two possibilities can explain that, although delayed, diabetes still occurred in anti-GITRL antibody-treated CD28−/− NOD mice." (PMID 19936238, 2009). "Nonobese diabetic (NOD) mice that lack CD28 signaling are deficient in CD4+ Tregs which results in exacerbated onset of spontaneous diabetes." (PMID 36761170, 2022).
diabetes (continued). "In this line of avaliation, 167 PCOS patients compared to 102 controls were evaluated and such study aimed at identifying coronary instability and diabetes mellitus type 2 through the frequency of CD4 (+) CD28 (null) lymphocytes that express the level of involvement by these morbidities." (PMID 26104466, 2015). "Under additive genetic models, CD28-rs3116494 (OR = 1.29 [95% CI 1.11, 1.51], P = 0.0011) and CD80-rs3850890 (OR = 1.16 [95% CI 1.02, 1.31], P = 0.0283) were associated with DKD susceptibility adjusted for age, gender, body mass index (BMI), duration of diabetes, and HbA1c." (PMID 33958973, 2021). "Specifically, patients with diabetes mellitus undergoing HD for half a year displayed an increase in CD3+CD8+, natural killer cells, CD4+CD28 null, and CD8+CD28 null." (PMID 41226416, 2025). "Two studies looked into the frequency of Treg cells and their PD-1 expression in the peripheral blood of patients with long-standing diabetes under basal conditions and after T-cell CD3/CD28 stimulation." (PMID 33672515, 2021). "We also examined the effects of diabetes and A-285222 treatment on cytokine secretion capacity of splenocytes under control non-stimulated conditions and after stimulation with anti-CD3/CD28 beads." (PMID 23755169, 2014). "We assessed the effects of increasing levels of IC87114 on T cells from diabetes-prone NOD mice in in vitro culture, looking at anti-CD3 and anti-CD28 induced proliferation of CD4+ T cells (left hand panel) and CD8+ T cells (right hand panel) and production of IFN-γ." (PMID 26783747, 2016). "However, the diabetes model employed was the CD28KO.NOD mouse in which the diabetogenic T cell response is, by definition, CD28-independent." (PMID 23849743, 2013). "Administration of this anti-GITRL antibody significantly delayed (but did not abrogate) diabetes development in CD28−/− NOD mice, as opposed to what observed with the agonist anti-GITR antibody." (PMID 19936238, 2009). "Moreover, B and T cell responses are altered in people with diabetes in several ways for instance, reduced expression of co-stimulatory molecules (CD69, CD28, CD40 ligand) or interleukin-12 receptor on T cells which leads to lower production of interferon and granzyme B." (PMID 36105809, 2022). "To study the effect of hyperglycemia on CD8+ T cell function, we stimulated peripheral blood mononuclear cells (PBMCs) from donors with and without diabetes with influenza A virus, anti-CD3/anti-CD28-coated beads, PMA and ionomycin (PMA/I), or an influenza viral peptide pool." (PMID 38214784, 2024). "Diabetes had no impact on the levels of cytokines produced by non-stimulated splenocytes, but resulted in significantly increased levels of TNF-α in cells stimulated with anti-CD3/CD28 beads." (PMID 23755169, 2014).
lupus (35 papers, 2009 to 2026). "In these group 1 lupus individuals, there was reduced CD28 expression on Th cells, an effect that has been linked to TNF-α signaling." (PMID 39688922, 2024). "CTLA-4/CD28 gene polymorphisms are genetically associated with several autoimmune diseases such as systemic lupus erythematosus (SLE), Graves’ disease, rheumatoid arthritis and Behçet’s disease." (PMID 25013611, 2011). "It is possible that anti-CD3 and anti-CD28 activated T cells contributed to the increased EGR2 expression in B cells from lupus mice MRL-lpr mice either through the release of cytokines or co-stimulatory signals." (PMID 32646370, 2020). "Lulizumab pegol, a pegylated Domain Antibody® targeting CD28 developed by Bristol-Myers Squibb, was evaluated in a phase II trial in subjects with active systemic lupus erythematosus (SLE)." (PMID 31544834, 2019). "These encouraging data generated in animal models indicate that selective CD28 blockade warrants further assessment in clinical lupus." (PMID 31548534, 2017). "We found that PP5 mRNA levels are significantly higher in CD4+CD28+ T cells from lupus patients relative to controls." (PMID 28239687, 2016). "We tested if PP5 is increased in CD4+CD28+ T cells by oxidative stress, if PP5 transfection causes overexpression of methylation sensitive genes in T cells, and if PP5 is overexpressed in lupus T cells." (PMID 28239687, 2016). "We therefore compared PP5 mRNA levels in CD4+CD28+ T cells freshly isolated from lupus patients with varying levels of disease activity to CD4+CD28+ T cells isolated from age and gender matched healthy volunteers." (PMID 28239687, 2016). "The PP5 over-expression is consistent with the decreased Dnmt1 levels and increased KIR, perforin, CD40L, CD70, and CD11a expression seen in CD4+CD28+ T cells from lupus patients." (PMID 28239687, 2016). "Elevated levels of soluble CD28 are found in serum from lupus patients, which can inhibit T-cell proliferation in vitro." (PMID 25606596, 2014). "Freshly isolated CD4+ T lymphocytes from pristane-induced lupus mice were activated with anti-CD3/CD28 antibodies (3 μg/ml) and interleukin-2 (IL-2) (200 U/ml) with or without resveratrol (0, 10, 20, 40, or 80 μM)." (PMID 25501752, 2014). "Although the local site of injury could not be fully presented with fidelity by studying T cells in the systemic level, we may provide new insights into the mechanism of CD4 + CD28− T cells related lupus tissue damage." (PMID 36320075, 2022). "Selective blockade of CD28 to preserve the generation of Tregs may therefore be a more efficacious approach for targeting costimulatory pathways in lupus." (PMID 31548534, 2017). "Subsequent studies used multicolor flow cytometry to demonstrate that these genes are co-overexpressed on the same CD3+CD4+CD28+ T cells, representing a previously unrecognized T cell subset, and that the size of this subset is directly related to lupus flare severity." (PMID 28620656, 2017). "CD4+CD28− stress-induced, PP5 overexpressing T cells have decreased ERK and JNK pathway signaling, low Dnmt1 levels, and overexpress methylation sensitive genes including KIR2DL4, CD70 and perforin, similar to the epigenetically altered CD4+CD28+ T cells from patients with active lupus." (PMID 28239687, 2016). "Further, chronic stimulation of the epigenetically altered CD4+CD28+KIR+ T cells found in lupus patients may contribute to their conversion to senescent CD4+CD28−KIR+ T cells." (PMID 28239687, 2016). "PP5 expression is increased in CD4+CD28+ T cells from lupus patients." (PMID 28239687, 2016). "Previous reports have associated increased CMV seropositivity with expansion of CD4 + CD28- T cells in RA, multiple sclerosis (MS) and systemic lupus erythematosus (SLE)." (PMID 32190092, 2020). "The presence of CD3/CD28 activated CD4+ T cells dramatically up-regulated PD-L1 expression on basophils, as observed in vivo in the lupus-like context." (PMID 38649353, 2024).
lupus (continued). "Purified human CD4+ T cells stimulated with anti-CD3 and anti-CD28 antibodies exhibited robust production of lupus-related pro-inflammatory cytokines (e.g., IFN-γ, TNF-α, IL-5, and IL-6) upon anti-CD3/CD28 beads stimulation." (PMID 39551768, 2024). "Some of the more recent failures in lupus trials include anti-CD20 (rituximab), anti-CD22 (epratuzumab), anti-BAFF (tabalumab, atacicept) CD28-Fc (abatacept), anti-IL6 (PF-04236921), and anti-IFN-α (sifalimumab)." (PMID 39452087, 2024). "We also analyzed the expression of EGR2 in different splenic cell subsets of a different murine lupus strain, B6.sle123 mice at resting state and following anti-CD3 and anti-CD28 stimulation." (PMID 32646370, 2020). "Together, our data suggested that EGR2 expresses at a low level in the resting T and B lymphocytes and that anti-CD3 and anti-CD28 stimulation significantly induces EGR2 expression in splenic T and B lymphocytes in both control and lupus mice." (PMID 32646370, 2020). "Clonal expansion of CD4+CD28− T cells is also detected in a peripheral circulation in other immune mediated disorders, such as multiple sclerosis, inflammatory bowel disease, and systemic lupus erythematosus (SLE)." (PMID 29370129, 2018). "PBMC from women with inactive and active lupus and inactive and active SS were isolated and stained with fluorochrome conjugated antibodies to CD3, CD4, CD28, CD70, CD40L and the KIR gene family then analyzed by multicolor flow cytometry." (PMID 28620656, 2017). "PP5 was found to be overexpressed in CD4+CD28+ T cells treated with H2O2 and ONOO− and in T cells from lupus patients." (PMID 28239687, 2016). "Positive co-stimulation through CD28 and negative regulation through CD152 are a major focus in designing immunotherapeutic agents to treat lupus patients." (PMID 25606596, 2014). "However, recent studies using RT-PCR analysis have shown that in systemic lupus erythematosus (SLE) patients, an increase in sCD28 levels results from shedding of membrane-bound CD28." (PMID 38243300, 2024). "In the murine lupus strain, New Zealand Black/New Zealand White F1, female mice treated with an artificial synthetic peptide (pConsensus) containing MHC class I and II determinants in the VH of an anti-DNA Ig, displayed increased CD8+ Tregs (CD28+ and CD28−)." (PMID 34831195, 2021). "In this study, we find that cytotoxic CD4+CD28- T cells are expanded in SLE patients with flow cytometry analysis, and the percentage of CD4+CD28- T cells positively correlates with the Systemic Lupus International Collaborating Clinics/ACR Damage Index (SDI)." (PMID 37415045, 2023). "In a second study, they reported that ICs isolated from systemic lupus erythematosus patients interact with CD16 expressed by CD4+ T cells and induce Syk phosphorylation, providing a co-stimulatory signal to T cells in the absence of CD28 signal." (PMID 30555482, 2018).